SARS1 (seryl-tRNA synthetase 1)
Description:
Catalyzes the attachment of serine to tRNA(Ser) in a two-step reaction: serine is first activated by ATP to form Ser-AMP and then transferred to the acceptor end of tRNA(Ser). Is probably also able to aminoacylate tRNA(Sec) with serine, to form the misacylated tRNA L-seryl-tRNA(Sec), which will be further converted into selenocysteinyl-tRNA(Sec). In the nucleus, binds to the VEGFA core promoter and prevents MYC binding and transcriptional activation by MYC. Recruits SIRT2 to the VEGFA promoter, promoting deacetylation of histone H4 at 'Lys-16' (H4K16). Thereby, inhibits the production of VEGFA and sprouting angiogenesis mediated by VEGFA.
Synonyms: SerRS; SARS; SERS; NEDMAS
Tractability: Small molecule: a structure with a bound ligand is known. PROTAC: ubiquitination databases record sites on it; a small molecule that binds it is known.
Target class: Enzyme; Ligase
Gene: Protein-coding gene on chromosome 1 (109,213,844 to 109,238,773, forward strand). Ensembl gene ENSG00000031698.
Subcellular location: Cytoplasm; Nucleus
Subcellular location (Human Protein Atlas): Cytosol
Pathways (Reactome):
Metabolism: Selenocysteine synthesis
Metabolism of proteins: Cytosolic tRNA aminoacylation
Gene Ontology:
Molecular function: enzyme binding; molecular adaptor activity; protein binding; protein homodimerization activity; RNA polymerase II cis-regulatory region sequence-specific DNA binding; selenocysteine-tRNA ligase activity; serine-tRNA ligase activity; tRNA binding; aminoacyl-tRNA ligase activity; ATP binding; nucleotide binding
Biological process: cytoplasmic translation; negative regulation of angiogenesis; negative regulation of transcription by RNA polymerase II; negative regulation of vascular endothelial growth factor production; selenocysteine incorporation; seryl-tRNA aminoacylation; tRNA C3-cytosine methylation; tRNA modification; translation; selenium compound metabolic process; tRNA aminoacylation for protein translation
Cellular component: cytoplasm; cytosol; extracellular exosome; nucleus; tRNA methyltransferase complex
Genetic constraint (gnomAD): Loss-of-function variants: 23 observed, 57.21 expected, observed/expected ratio (o/e) 0.4, 90% interval 0.29 to 0.57. The upper end of that interval is the gene's LOEUF score, 0.57, which puts it in group 2 of 6, group 1 being the genes least tolerant of losing a copy. Missense variants: 375 observed, 592.35 expected, observed/expected ratio (o/e) 0.63, 90% interval 0.58 to 0.69. Synonymous variants: 211 observed, 222.21 expected, observed/expected ratio (o/e) 0.95, 90% interval 0.85 to 1.06.
Gene-disease validity (ClinGen):
ClinGen rates the evidence that SARS1 causes each of these diseases.
neurodevelopmental disorder with microcephaly, ataxia, and seizures (autosomal recessive): Limited.
Homologues: Orthologues: chimpanzee SARS1 (99% identical), macaque SARS1 (99% identical), rabbit SARS1 (97% identical), guinea pig SARS1 (96% identical), dog SARS1 (96% identical), mouse Sars1 (96% identical), rat Sars1 (95% identical), pig SARS1 (95% identical), zebrafish sars1 (82% identical), tropical clawed frog sars1 (81% identical), Drosophila melanogaster SerRS (67% identical), Caenorhabditis elegans sars-1 (63% identical). Paralogues in human: SARS2 (23% identical).
Diseases named in the same sentence as SARS1 in open-access papers:
SARS1 is named in the same sentence as 21 diseases in open-access papers, as found by Europe PMC text mining. Sharing a sentence is not in itself a finding about the gene and the disease. The quoted sentences say what the papers report.
cardiomyopathy (2 papers, 2022 to 2026). A disease of the heart muscle or myocardium proper. "Seryl-tRNA synthetase 1 (SARS1) deficiency is a rare autosomal recessive disorder presenting with neurodevelopmental delay, deafness, cardiomyopathy, and fatal metabolic decompensation triggered by febrile episodes." (PMID 42158840, 2026).
COVID-19 (2 papers, 2020 to 2025). A disease caused by infection with severe acute respiratory syndrome coronavirus 2. "Wild type mice (BALB/c, C57BL/6), immunodeficient mice (SCID), chimeric mouse expressing human angiotensin-converting enzyme 2 (hACE2), and the RNA-dependent RNA polymerase (SARS1/SARS2-RdRp) were evaluated as models of COVID-19." (PMID 33023604, 2020).
microcephaly (2 papers, 2022 to 2025). A congenital or acquired developmental disorder in which the circumference of the head is smaller than normal for the person's age and sex. "With reference to aminoacyl-tRNA synthetase, a study on ARS deficiencies showed that serine supplementation ranging from 85.7 to 97.5 mg/kg/day in fibroblasts of patients with Seryl-tRNA synthetase 1 (SARS) enabled improvements in height and development, as well as resolution of microcephaly." (PMID 40428324, 2025).
Ataxia (1 paper, 2022). Ataxia refers to impaired coordination of voluntary muscle movement. "In this study, WES identified for the first time a de novo variant in SARS1, challenging the described recessive mode of inheritance, in a patient affected with complex spastic paraparesis with ataxia, seizures and intellectual disability." (PMID 36041817, 2022).
Cerebellar atrophy (1 paper, 2020). Cerebellar atrophy is defined as a cerebellum with initially normal structures, in a posterior fossa with normal size, which displays enlarged fissures (interfolial spaces) in comparison to the foliae secondary to loss of tissue. "Microcephaly with cerebellar atrophy was reported to result from defects in glutaminyl-tRNA synthetase 1 (QARS1) or defects in seryl-tRNA synthetase 1 (SARS1)." (PMID 33102526, 2020).
Charcot-Marie-Tooth (CMT) disease (1 paper, 2023). "Thus far, autosomal dominant mutations in AARS1, GARS1, HARS1, MARS1, WARS1, SARS1 and YARS1 have been linked to peripheral neuropathies, predominantly Charcot-Marie-Tooth (CMT) disease." (PMID 37274211, 2023).
focal epilepsy (1 paper, 2025). A seizure caused by a localized disorder. "A de novo deleterious variant in SARS1 (Pro226His) (VUS) was found in patient EPBL-0165 with focal epilepsy." (PMID 40565278, 2025).
infection (4 papers, 2020 to 2022). The state of being infected such as from the introduction of a foreign agent such as serum, vaccine, antigenic substance or organism. "Similarly, OC43 and SARS1 infection were predicted to inhibit apoptosis and necrosis, whereas infection by the more pathogenic SARS-CoV-2 was predicted to activate necrosis and apoptosis." (PMID 36299731, 2022). "Both SARS1 and SARS2 utilize their RBD of the spike protein to engage human ACE2 on host cells for infection, making RBD a primary target for neutralizing antibody development." (PMID 36494344, 2022). "figshare File F1 contains the full human SARS1 (Section 2), SARS2 (Section 3), MERS (Section 4) and IAV (Section 5) infection transcriptomic consensomes." (PMID 32511379, 2020).
cancer (2 papers, 2020 to 2025). A tumor composed of atypical neoplastic, often pleomorphic cells that invade other tissues. "At the RNA level, SARS1 is only upregulated in two out of 33 cancer types (DLBC and THYM), the lowest number among all aaRSs." (PMID 33266490, 2020). "NARS1 and SARS1 stand out as the two most cancer-inhibiting aaRSs." (PMID 33266490, 2020). "While SARS1 is altered with a low frequency (1.5%) of both amplifications and deletions, the alterations of SARS2 in cancer patients are more frequent (2.8%) and mostly consist of gene amplifications." (PMID 33266490, 2020). "In contrast to the pro-angiogenic activity of TARS1, SARS1 possesses anti-angiogenic activity through its nuclear presence, which may explain its lack of amplification in cancer tissues." (PMID 33266490, 2020).
movement disorder (1 paper, 2024). Neurological conditions resulting in abnormal voluntary or involuntary movement, which may impact the speed, fluency, quality and ease of movement. "Pathogenic variants in the SARS1 gene encoding cytosolic SerRS have been implicated in neurodevelopmental, neurological, and movement disorders with various symptoms." (PMID 38255739, 2024).
neurodevelopmental disorder (1 paper, 2022). A behavioral and cognitive disorder with onset during the developmental period that involves impaired or aberrant development of intellectual, motor, or social functions. "We refine the phenotypic spectrum and modes of inheritance of a newly described, ultrarare neurodevelopmental disorder, while unveiling the role of SARS1 as a regulator of cell growth, division and senescence." (PMID 36041817, 2022).
tumor (1 paper, 2020). "NARS1 and SARS1 are also downregulated in two tumor types (LAML for both genes and LUSC and KIRC for SARS1 and NARS1, respectively)." (PMID 33266490, 2020). "Therefore, exploring the tumor suppressor activities of NARS1 and SARS1 represents an interesting direction for future studies." (PMID 33266490, 2020).
SARS1 also shares sentences with these, for which no sentence is quoted: breast carcinoma (1 paper); deafness (1); epilepsy (1); Intellectual disability (1); melanoma (1); Moderate intellectual disability (1); Neurodevelopmental delay (1); Seizure (1); Spastic paraplegia (1).